CRP (C-reactive protein)
Diseases named in the same sentence as CRP in open-access papers (continued):
Sharing a sentence is not in itself a finding about the gene and the disease.
periodontitis (continued). "Median CRP levels were higher in the periodontitis group (39.30 vs. 35.79; p < 0.001)." (PMID 41420778, 2025). "HNC cases were identified using ICD-10 codes, with CRP and periodontitis as key predictors." (PMID 40076898, 2025). "Chronic infections, including periodontitis, might increase circulating cytokines and factors, such as C-reactive protein, interleukin-1 beta, interleukin-6, tumor necrosis factor-alpha, and prostaglandin-E2." (PMID 39229981, 2025). "Periodontitis may be classified as a “low-grade systemic disease” due to the release of proinflammatory cytokines into the bloodstream and increased C-reactive protein (CRP) levels." (PMID 40283848, 2025). "Once periodontitis establishes, inflammatory cytokines and endotoxins (lipopolysaccharide) are released, leading to elevated systemic levels of neutrophils, CRP, and IL-1, which might amplify inflammatory response, potentially increasing the danger of APOs." (PMID 39906598, 2025). "Collectively, these findings support the hypothesis that systemic inflammation—particularly as mediated by CRP—is a critical mechanistic pathway through which gut microbiota-targeted dietary patterns influence the onset and progression of periodontitis." (PMID 40880748, 2025). "Our findings are in line with literature data reporting CRP overproduction during periodontitis." (PMID 41011406, 2025). "This contrasts with previous studies that reported significant reductions in CRP following periodontal therapy, likely due to differences in study populations; prior studies included individuals with more severe periodontitis and higher baseline CRP levels than our cohort." (PMID 40319277, 2025). "Preeclampsia, initiated by periodontitis, results in elevated IL-6 and CRP in early pregnancy." (PMID 41394354, 2025). "Cytokines, such as interleukin-1β (IL-1β), tumor necrosis factor-alpha (TNF-α), and acute-phase proteins, including CRP, which are secreted during periodontitis, enhance systemic inflammation, which in turn aggravates endothelial dysfunction and plaque formation." (PMID 40418274, 2025). "Elevated serum levels of high-sensitivity C-reactive protein (hs-CRP) have been consistently observed in patients with chronic periodontitis compared with healthy controls, suggesting that local oral inflammation may mirror systemic immune activation." (PMID 41463662, 2025). "In addition, low serum vitamin C levels were correlated with more severe forms of periodontitis and higher levels of C-reactive protein." (PMID 40422620, 2025). "Individuals with periodontitis exhibit increased serum levels of inflammatory markers, such as C-reactive protein (CRP) and interleukin-6 (IL-6), suggesting that EtO may exacerbate inflammation." (PMID 40430168, 2025). "Severe periodontitis leads to an increase in the levels of C-reactive protein, interleukin- 1 (IL- 1), and IL-6, which may work synergistically with the toxins in cigarette smoke to exacerbate inflammatory changes in tissues and organs." (PMID 39582409, 2025). "In this study, instead, periodontal status was predicted using common systemic indicators, offering new insights into how markers such as CRP and other systemic health indicators may support the early diagnosis of periodontitis in non‐dental settings." (PMID 40701837, 2025). "Periodontitis with high CRP levels may indicate a high mortality rate, indicating the importance of active monitoring and intensive management of periodontitis and inflammatory markers." (PMID 39453923, 2024). "The presence of systemic variables could be a confounding factor in the evaluation of the effect of periodontitis on CRP levels." (PMID 38195732, 2024). "Pathogens linked to periodontitis, such as Porphyromonas, Fusobacterium, and Treponema, are more abundant in the subgingival plaques of HTN participants and are positively correlated with IL-6 and/or CRP levels." (PMID 39203574, 2024).
periodontitis (continued). "Reports from a meta-analysis showed that periodontitis therapy lowered systemic inflammation via reductions in both high-sensitivity CRP (hs-CRP) [0.56 mg/L, 95% confidence interval (CI) (−0.88, −0.25), p < 0.001] and IL-6 [0.48 pg/mL, 95% CI (−0.88, −0.08), p = 0.020] levels." (PMID 38667035, 2024). "The participants with both periodontitis and CRP levels of > 0.5 mg/dL had the highest HR of 2.01." (PMID 39453923, 2024). "The synergy between periodontitis and CRP levels may have a biological basis, given that they both possess similar pathophysiological pathways that can result in CVD-related death or all-cause mortality." (PMID 39453923, 2024). "Understanding the intricate interplay between Galectin-3, NLRP3, suPAR, CRP, and periodontitis requires further studies, which could lead to pivotal findings for elucidating disease mechanisms and identifying potential therapeutic targets." (PMID 39453923, 2024). "Additionally, a clinical study found that periodontitis therapy significantly reduced levels of inflammatory factors IL-6, IL-8, and CRP in patients with atherosclerotic cardiovascular disease with high CRP levels (CRP ≥ 3 mg/L)." (PMID 39203574, 2024). "Increased circulating levels of CRP have been reported in periodontitis as well as in CVD patients." (PMID 38667035, 2024). "However, this study is the first to demonstrate the synergy between periodontitis and CRP levels, even after adjusting for confounders." (PMID 39453923, 2024). "Reviews of studies have shown that erythrocyte sedimentation rate and C- reactive protein levels may be raised in rheumatoid arthritis patients with periodontitis." (PMID 39917647, 2024). "The highest titers for MIP-1α and CRP were detected among patients with periodontitis with and AMI." (PMID 38433948, 2024). "Elevated CRP levels have also been observed in patients with periodontitis." (PMID 39595081, 2024). "Also, evidence has shown a positive relationship between increased CRP and the severity of periodontitis." (PMID 39494478, 2024). "In this study, NSPT significantly decreased CRP levels in patients with periodontitis." (PMID 38877442, 2024). "Moreover, the impact of periodontitis on serum hs-CRP levels in patients with ESRD significantly correlated with the periodontitis severity (2.4, 4.2, and 4.4 mg/L in the slight, moderate, and severe periodontal tissue breakdown, respectively)." (PMID 38846514, 2024). "Periodontitis, a potential risk factor for CVD, has been suggested to be associated with serum levels of these molecules, adiponectin, and other inflammatory mediators, such as tumor necrosis factor-alpha (TNF-α) and C-reactive protein (CRP) as well." (PMID 37371602, 2023). "The level of serum CRP dramatically increased with the severity of periodontitis." (PMID 37575815, 2023). "A study in an Italian population also assessed that a family history of T2DM, poor glycemic control, and C-reactive protein (CRP) levels could be the effective predictors of the onset and progression of severe periodontitis." (PMID 37664859, 2023). "In addition to elevated pro-inflammatory mediator levels, patients with periodontitis exhibit distinct haematological alterations, including elevated C-reactive protein (CRP) levels." (PMID 37568846, 2023). "Another marker for inflammation is the high levels of C-reactive proteins (CRP): a study described a positive correlation between periodontitis and high levels of CRP, and patients with severe periodontitis have increased serum levels of CRP when compared with the unaffected control population." (PMID 36981618, 2023). "IL-6 and CRP levels on the severity of periodontitis in CAD in Indonesia were also evaluated." (PMID 37239434, 2023). "Additionally, it has been documented that periodontitis increases systemic inflammation markers, such as interleukin-6 (IL-6) and C-reactive protein (CRP)." (PMID 37568161, 2023).
periodontitis (continued). "IL-6 -572 C/G, CRP -757 A/G, and CRP -717 T/C gene polymorphisms; IL-6 levels; and CRP levels had no apparent effects on the severity of chronic periodontitis in CAD based on the path analysis." (PMID 37239434, 2023). "In terms of relative importance of variables to instruct the algorithms for periodontitis prediction, the most significant contribution to learning came from age, CRP, and sex, followed by smoking, while the MetS components did not substantially contribute to prediction." (PMID 37038173, 2023). "In this regard, the purpose of the present randomized clinical trial (RCT) was to evaluate the effect of NSPT performed either through Q-SRP or FMD on GDF-15, GPx-1, hs-CRP, and SP-D concentrations in patients with periodontitis at 6-month follow-up after treatment." (PMID 37605193, 2023). "CRP levels/BMI measurements were taken and participants were evaluated for periodontitis." (PMID 37481511, 2023). "From there, the inflammatory response during periodontitis has been shown to be marked by the local release of specific proinflammatory mediators and enzymes, including C-reactive protein (CRP); metalloproteinases (MMPs); interleukin- (IL-) 1β, IL-6, and IL-10; and tumor necrosis factor (TNF-α)." (PMID 37214190, 2023). "No studies have focused on the CRP -757 A/G and CRP -717 T/C gene polymorphisms for chronic periodontitis in CAD." (PMID 37239434, 2023). "A significant relationship has been reported between CRP -757 T/C and chronic periodontitis." (PMID 37239434, 2023). "Healthy eating habits, especially increased dietary fibre intake, may improve periodontitis markers by reducing serum CRP levels." (PMID 37198606, 2023). "More aggressive forms of periodontitis presented a 50% greater rise in CRP levels in serum." (PMID 38139161, 2023). "Similarly, patients with periodontitis had significantly higher levels of high-sensitivity C-reactive protein (hs-CRP) than healthy individuals." (PMID 37240630, 2023). "It is possible that gingival inflammation in periodontitis may mask the association between blood and GCF CRP levels." (PMID 38138192, 2023). "Polymorphisms were not affected by the severity of chronic periodontitis, IL-6 levels, and CRP levels." (PMID 37239434, 2023). "The CRP increase in periodontitis is due to the fact that the chronic inflammation process of this disease increases systemic pro-inflammatory cytokines, which would lead to the upregulation of inflammation markers such as CRP." (PMID 37568161, 2023). "CRP is a major parameter for treating CAD patients with periodontitis." (PMID 37239434, 2023). "Moreover, the CRP levels in the mild periodontitis and moderate–severe periodontitis groups were 7.675 ± SD 9.143 and 9.420 ± 15.548, respectively." (PMID 37239434, 2023). "Another study showed the presence of CRP and IL-6 in periodontitis patients with CAD." (PMID 37239434, 2023). "Several studies reported that the involvement of CRP and CAD is associated with periodontitis." (PMID 37239434, 2023). "In long-term infections such as periodontitis, high serum CRP levels and other proinflammatory circumstances may promote systemic inflammation and oxidative stress, leading to IR, which are features of PCOS." (PMID 38021744, 2023). "The higher CRP levels in the group with severe periodontitis could be attributed to more periodontal inflammation." (PMID 36316604, 2023). "Interestingly, IL-6 levels affected CRP levels in periodontitis patients with CAD (path coefficient 0.322, p = 0.003)." (PMID 37239434, 2023). "In this study, we speculated on the relationship between CRP and periodontitis in the obese population." (PMID 37481511, 2023). "The relationship between periodontitis and CRP has received great attention due to a link between periodontitis and systemic diseases including cardiovascular disease and because of periodontal treatment effects on the level of CRP." (PMID 38139161, 2023).
periodontitis (continued). "In periodontitis, inflammatory markers, such as C-reactive protein (CRP), and pro-inflammatory cytokines, such as Tumor Necrosis Factor α (TNFα), are increased, which eventually may be associated with cognitive decline in AD patients." (PMID 36289921, 2022). "Periodontitis patients presented higher CRP levels, while NPG patients had higher GGT (p < 0.05)." (PMID 35866675, 2022). "In addition, patients with severe periodontitis have elevated levels of inflammatory mediators, such as IL-1, IL-6, C-reactive protein (CRP), and fibrinogen, in their blood." (PMID 36329504, 2022). "The impact of NSPT on the reduction of CRP in patients of CAD with periodontitis is significant." (PMID 36243997, 2022). "Collectively, these findings suggest that reduced levels of CRP, IL-6, TNFα, and IL-1β after treatment of periodontitis could restore eNOS activity and NO bioavailability, resulting in improved endothelial dysfunction." (PMID 35874771, 2022). "Also, this trend was seen for the number of patients with an elevated CRP level (>3 mg/L) among the control group (7.0%), localized (21.3%) and generalized (27.5%) periodontitis patients (p = .002)." (PMID 36794206, 2022). "Similarly, white blood cell, D‐dimer, and CRP levels were significantly higher in COVID‐19 patients with periodontitis in this study." (PMID 35578891, 2022). "NE and CRP are markers of systemic inflammatory burden and may be part of the link that connects the oral inflammation periodontitis with other parts of the body." (PMID 35683571, 2022). "Within the limitations of the present study, the following conclusion may be drawn: In untreated grade C periodontitis (CP), serum NE and CRP are higher than in grade B periodontitis (BP)." (PMID 35683571, 2022). "However, the periodontitis group showed higher C-reactive protein levels, while NPG showed higher gamma-glutamyl transpeptidase levels (p < 0.05)." (PMID 35866675, 2022). "The increase of CRP level could also be detected in the serum of T2D mice with periodontitis, which not only promoted periodontal inflammation, but also accelerated the development of diabetes." (PMID 36131931, 2022). "However, periodontitis also triggers systemic inflammation, indicated by an increased level of C-reactive protein (CRP), TNFα, IL-1β, and IL-6 in the serum of patients." (PMID 35874771, 2022). "Total CRP was higher in the periodontitis group and was lower in the HC1/3 group." (PMID 35720191, 2022). "Similarly, in experimental periodontitis, there is an increase in the circulating levels of CRP, IL-1β, IL-6, and of neutrophils." (PMID 35052857, 2022). "Furthermore, morbidly obese patients with periodontitis had higher CRP levels, while those with gingivitis presented higher GGT levels." (PMID 35866675, 2022). "Therefore, patients with periodontitis often present elevated levels of C-reactive protein (CRP), which is a parameter used to determine systemic inflammation." (PMID 35692596, 2022). "Moreover, significant increases in alanine aminotransaminase, AST, C-reactive protein, and endotoxin levels were observed in the periodontitis rats with P. gingivalis." (PMID 33918456, 2021). "Thus, it is the objective of this study to assess the quandaries in the relationship between the systemic and local sources of CRP and fibrinogen from adiposity and from periodontitis, respectively." (PMID 32827080, 2021). "Previous systematic reviews suggested elevated CRP levels in patients with periodontitis." (PMID 34394107, 2021). "Periodontitis treatment can reduce serum CRP levels in patients with CKD." (PMID 34211440, 2021). "The presence of generalized or severer forms of periodontitis, with higher levels of destruction and chronicity, may trigger a greater systemic inflammation and higher levels of CRP in the blood." (PMID 34439905, 2021). "The exact mechanism of how periodontitis triggers CRP release is still under investigation." (PMID 34394107, 2021).
periodontitis (continued). "Periodontitis may impair blood glucose regulation in healthy subjects in conjunction with elevated CRP levels." (PMID 33435628, 2021). "A different study observed higher concentrations of salivary CRP in participants with chronic periodontitis compared to healthy controls and may suggest that salivary CRP indicates increased inflammation in the oral cavity due to local disease." (PMID 33807159, 2021). "Additionally, the same research group examined 2481 Germans to analyze the relationships between serum CRP levels, periodontitis, and NAFLD." (PMID 33918456, 2021). "Today, predominant opinion connects the local inflammation of periodontitis with chronic systemic inflammatory diseases via mediating pathways characterized by various indicators of inflammation such as fibrinogen, C-reactive protein (CRP), and interleukin IL-6." (PMID 32827080, 2021). "A one-unit rise in both serum HbA1c and hs-CRP could increase the odds for having severe periodontitis by approximately 60%." (PMID 33924022, 2021). "One of the main findings of our study was that poor glycemic control was related to severity of periodontitis and that periodontal disease could increase the amount of plasma CRP." (PMID 33804123, 2021). "Beyond the effect of the treatment of periodontitis in reducing CRP, the clinical relevance of the observed acute increase in inflammation after an intensive NSPT is still unknown, particularly in patients with other comorbidities." (PMID 34394107, 2021). "In a longitudinal study, periodontitis was associated with increased serum CRP levels and CVD mortality in men, but not in women." (PMID 34439905, 2021). "The aim of this study was to investigate the relationship between blood biomarkers and serologic immunological profiles related to periodontitis (CRP, LPS, and serum anti- Aggregatibacter actinomycetemcomitans [Aa] and anti-Porphyromonas gingivalis [Pg] IgG) in abdominal aortic aneurysm patients." (PMID 35096635, 2021). "One study demonstrated that CRP levels increase with the severity of periodontitis." (PMID 32994872, 2020). "Additionally, almost all studies have evaluated the relationship between periodontitis and CRP in individuals with some comorbidity, especially cardiovascular disease." (PMID 32994872, 2020). "Moreover, CRP, as a biomarker of systemic inflammation, reflects chronic inflammatory status due to periodontitis, and treating a periodontal infection can significantly lower serum CRP levels." (PMID 32512870, 2020). "In this scenario, the hypothesis that individuals with periodontitis present modified levels of CRP has been raised." (PMID 32994872, 2020). "Concentrations of CRP in the hippocampus and cerebral cortex of rats with AD and periodontitis." (PMID 32614834, 2020). "The presence of CRP in GCF could be a result of systemic inflammation induced by periodontitis or disease elsewhere in the body." (PMID 33488610, 2020). "Therefore, several studies have been conducted on the possible correlation between periodontitis and CRP level." (PMID 33424972, 2020). "Many studies have reported an increased CRP level in the presence of periodontitis." (PMID 33424972, 2020). "Key words:C-reactive protein, cytokines, periodontal diseases, periodontitis." (PMID 32994872, 2020). "Not all of these studies found an association between periodontitis and CRP; the findings differed according to the severity of the periodontitis, the degree of progression, and the target population." (PMID 33424972, 2020). "The predictive factors in the model were older age, higher CRP level, combined DMARDs-corticoids therapy, greater mean CAL at baseline, and fewer sites with bleeding, which predicted approximately 85% of the risk of periodontitis progression." (PMID 31703715, 2019).